TRGV1 (T cell receptor gamma variable 1 (non-functional))
Description:
Probable non-functional open reading frame (ORF) of V region of the variable domain of T cell receptor (TR) gamma chain. Non-functional ORF generally cannot participate in the synthesis of a productive T cell receptor (TR) chain due to altered V-(D)-J or switch recombination and/or splicing site (at mRNA level) and/or conserved amino acid change (protein level). Gamma-delta TRs recognize a variety of self and foreign non-peptide antigens frequently expressed at the epithelial boundaries between the host and external environment, including endogenous lipids presented by MH-like protein CD1D and phosphoantigens presented by butyrophilin-like molecule BTN3A1. Upon antigen recognition induces rapid, innate-like immune responses involved in pathogen clearance and tissue repair. Binding of gamma-delta TR complex to antigen triggers phosphorylation of immunoreceptor tyrosine-based activation motifs (ITAMs) in the CD3 chains by the LCK and FYN kinases, allowing the recruitment, phosphorylation, and activation of ZAP70 that facilitates phosphorylation of the scaffolding proteins LCP2 and LAT. This lead to the formation of a supramolecular signalosome that recruits the phospholipase PLCG1, resulting in calcium mobilization and ERK activation, ultimately leading to T cell expansion and differentiation into effector cells. Gamma-delta TRs are produced through somatic rearrangement of a limited repertoire of variable (V), diversity (D), and joining (J) genes. The potential diversity of gamma-delta TRs is conferred by the unique ability to rearrange (D) genes in tandem and to utilize all three reading frames. The combinatorial diversity is considerably increased by the sequence exonuclease trimming and random nucleotide (N) region additions which occur during the V-(D)-J rearrangements.
Synonyms: V1S1P; TCRGV1
Gene: T-cell receptor variable (V) gene on chromosome 7 (38,367,586 to 38,368,169, reverse strand). Ensembl gene ENSG00000211701.
Subcellular location: Cell membrane
Gene Ontology:
Cellular component: plasma membrane
Homologues: Orthologues: mouse Trgv7 (46% identical). Paralogues in human: TRGV4 (80% identical), TRGV3 (78% identical), TRGV2 (76% identical), TRGV5 (74% identical), TRGV8 (72% identical), TRGV9 (26% identical), TRGV11 (26% identical), TRGV10 (24% identical), TRGC1 (0% identical), TRGC2 (0% identical).
Diseases named in the same sentence as TRGV1 in open-access papers:
TRGV1 is named in the same sentence as 2 diseases in open-access papers, as found by Europe PMC text mining. Sharing a sentence is not in itself a finding about the gene and the disease. The quoted sentences say what the papers report.
tumor (2 papers, 2023 to 2024). "The expression of Trgv1, the gene encoding T cell receptor Vγ1 chain, but not Trgv4, Trgv5, Trgv6 or Trgv7 was also upregulated in tumours of Vil Apc Dock2 mice." (PMID 39242821, 2024).
TRGV1 also shares sentences with these, for which no sentence is quoted: prostate tumors (1 paper).